HMGB1 (high mobility group box 1)
Diseases named in the same sentence as HMGB1 in open-access papers (continued):
Sharing a sentence is not in itself a finding about the gene and the disease.
cancer (1,108 papers, 2008 to 2026). A tumor composed of atypical neoplastic, often pleomorphic cells that invade other tissues. "Upregulation of HMGB1 was significantly associated with longer cancer-specific survival (CSS) and overall survival (P < 0.01 and P = 0.02, respectively)." (PMID 41777952, 2026). "Background/Objectives: Aberrant expression of high-mobility group protein B1 (HMGB1) has been linked to cancer development and progression." (PMID 40804938, 2025). "It has been reported that HMGB1 is upregulated in cancer tissue samples and is positively associated with poor prognosis in cancer patients in relation to HMGB1-induced DDR." (PMID 40244228, 2025). "In cancer, ferroptosis inhibition is directly associated with therapy resistance, and HMGB1 has emerged as an integrator of ferroptotic signaling, inflammatory activation, and therapy resistance." (PMID 41465435, 2025). "HMGB-1, a well-known danger signal, has been implicated in inflammation, cell proliferation, immunity, metabolism, cancer, and oxidative stress." (PMID 41226929, 2025). "Remarkably, TLR4 and AGER share a common ligand, the high-mobility group box 1 (HMGB1), a damage-associated molecule extensively implicated in cancer pathogenesis." (PMID 40647480, 2025). "The comprehensive evaluation across RAGE expression, cell viability, and apoptosis assays supports Paliperidone’s multifaceted potential as a therapeutic agent targeting cancer cells, particularly in contexts where HMGB1-mediated pathways are implicated." (PMID 39940823, 2025). "With further research on HMGB1, HMGB1 has been shown to be associated with cancer hallmark features proposed by Hanahan." (PMID 40969278, 2025). "The interplay between HIF-1α, NF-ĸB, and HMGB1 sustains DNA damage and the accumulation of mutations, driving cancer progression and worsening prognosis." (PMID 40244228, 2025). "HMGB1 also exerts a critical oncogenic role by bidirectionally regulating the functional states of DCs and cancer‐associated fibroblasts (CAFs), synergistically shaping an immune‐suppressive and stroma‐remodeling TME." (PMID 41354099, 2025). "Future studies should focus on elucidating the molecular mechanisms underlying the varying expression of HMGB1 and its impact on T cells, potentially leading to the identification of novel biomarkers and therapeutic targets for cancer treatment." (PMID 39268081, 2024). "In the cytoplasm, HMGB1 is mainly associated with the regulation of autophagy in cancer cells, a degradation of dysfunctional organelles and proteins to generate metabolic fuels during starvation." (PMID 39830522, 2024). "Cisplatin and oxaliplatin cause the secretion of high mobility group box 1 (HMGB1) from cancer cells, which is necessary for initiation of immunogenic cell death (ICD)." (PMID 38496553, 2024). "Preclinical and clinical studies have identified that CaEP treatment leads to a release of damage-associated molecular patterns (DAMPs) from necrotising cancer cells, including adenosine-triphosphate (ATP) and high-mobility group box 1 (HMGB1)." (PMID 38804839, 2024). "Numerous illnesses, such as cancer, autoimmune disorders, and AD, are associated with elevated HMGB1 levels." (PMID 39347125, 2024). "While HMGB1 secreted by cancer cells is implicated in inducing cachexia in CRC patients, its link to myocardial damage remains elusive." (PMID 38731953, 2024). "Then, these ions cause cancer cell death by mediating a hypertonic state in which cells secrete adenosine triphosphate (ATP) and high mobility group box 1 (HMGB-1) for stimulation of ICD." (PMID 38566199, 2024). "During ICD, cancer cells release damage-associated molecular patterns (DAMPs) such as calreticulin, high-mobility group box 1 (HMGB1), and adenosine triphosphate (ATP)." (PMID 39539554, 2024). "For instance, the pro-inflammatory cytokine IL-1β and immune-activating damage-associated molecule HMGB1 can promote cancer development and progression." (PMID 38831013, 2024).
cancer (continued). "Given that extracellular HMGB1 is implicated in inflammation and cancer, ELISA was then applied to test the quantity of HMGB1 in the culture fluid." (PMID 38469295, 2024). "This increased DNA damage is linked to increased cytoplasmic translocation and extracellular release of high mobility group box 1 (HMGB1) in PIR-deficient cancer cells." (PMID 39534872, 2024). "The HMGB1 pathway has been implicated in several diseases, including inflammation, autoimmune disorders, and cancer." (PMID 39347125, 2024). "M2-like macrophages and high mobility group protein B1 (HMGB1) are tightly linked to fundamental aspects of human malignancies, including invasion, metastasis, and the cancer microenvironment." (PMID 39061213, 2024). "HMGB1 overexpression has been associated with a poor prognosis in various types of cancer (e.g., breast, lung, and colorectal)." (PMID 38725632, 2024). "Secretion of HMGB1 from cancer-associated fibroblasts (CAFs) promotes metastatic potential of non-small cell lung cancer cells." (PMID 36982351, 2023). "In contrast, HMGB1-mediated lysosome metabolic blockade in cancer cells is strongly linked to antitumor effects by promoting cytoplasmic translocation of HMGB1." (PMID 37537587, 2023). "Since cancer relapse is predominantly associated with the activation of pro-survival autophagy and HMGB1 has been demonstrated to regulate this process, we analyzed the most abundant marker of autophagy, LC3 I/II." (PMID 37880798, 2023). "A pathogenic role of HMGB1 was identified in many cancers, chronic inflammatory processes, or even autoimmune disorders." (PMID 37998605, 2023). "Subsequently, hypoxia-induced cancer cell death releases damage-associated molecular patterns (DAMPs), such as high mobility group box 1 (HMGB1), which recruit immune cells into the TIME." (PMID 37127629, 2023). "Extracellular HMGB1 is elevated in many patients and mice with cancer and is typically associated with poor prognosis and reduced survival." (PMID 36831371, 2023). "Since HMGB1 is closely associated with cancer development, we investigated the role of HMGB1 in the pathogenesis of Kaposi’s sarcoma (KS)." (PMID 37520371, 2023). "HMGB1 over-expression is extensively associated with cancer, including those of the prostate and ovary, and it has been demonstrated that HMGB1 silencing slows cell growth and inhibits the growth of xenograft tumors in nude mice." (PMID 37110415, 2023). "HMGB1 induces autophagy through multiple pathways in cancer, and loss of HMGB1 in macrophages results in the suppression of autophagy." (PMID 36658496, 2023). "The invasiveness and migration of human NSCLC cells is also mediated by HMGB1, which is released from autophagic cancer-associated fibroblasts as shown in vitro in nude mouse studies." (PMID 36831371, 2023). "Specifically, following chemotherapy, dying cancer cells release immunostimulatory molecules such as ATP, calreticulin and High Mobility Group Box 1 (HMGB1), collectively known as Damage‐Associated Molecular Patterns (DAMPs)." (PMID 36646904, 2023). "The combined use of autophagy inhibitors 3-Methyladenine (3-MA) and YC-1 (an inhibitor of HIF-1α), attenuated HMGB1 release in cancer cells, indicating a potential underlying mechanism regulating extracellular levels of HMGB1 and autophagy in OSCC cells." (PMID 37511951, 2023). "Paradoxically, it has been reported that HMGB1 was associated with various cancer progression and poor outcomes." (PMID 37325669, 2023). "We present estimates of nuclear histone densities in 373 cancer cell lines, based on Cancer Cell Line Encyclopedia data, and we show that a known histone regulator, HMGB1, is linked to histone density aberrations in many cancer cell lines." (PMID 36030322, 2022). "HMGB1 expression was found to be significantly correlated with cancer-associated fibroblast and CD8+ T cell infiltration in the TME." (PMID 36230798, 2022).
cancer (continued). "We have demonstrated that HMGB1 secreted by autophagic cancer-associated fibroblasts is critical for promoting the progression of luminal breast cancer." (PMID 35193644, 2022). "Compelling evidence has indicated the association of HMGB1 with various hallmarks of cancer, such as angiogenesis, apoptosis, tissue invasion, metastasis, inflammation, and insensitivity to growth inhibitors." (PMID 36428714, 2022). "As a significant damage-associated molecular pattern (DAMP), HMGB1 is an essential protein for the immunogenic cell death (ICD) of cancer cells." (PMID 36438923, 2022). "The interaction of RAGE/TLRs with HMGB1 is associated with the growth, progression, and metastasis of malignant tumors." (PMID 36613714, 2022). "Certain published studies have shown a functional association between HMGB1 and clinically related diseases, especially different types of cancer." (PMID 36230798, 2022). "In different cell types, including glioblastoma cells or cancer associated fibroblasts (CAFs), HMGB1 secretion was dependent on the lipidation machinery components such as ATG5." (PMID 36601581, 2022). "Studies have shown that HMGB1 plays an important role in promoting or suppressing tumorigenesis in various cancers, including CRC, and is associated with prognosis." (PMID 35354479, 2022). "SA of HMGB1 has been linked to several crucial roles in cancer progression both in the cancer cells themselves as well as in the tumor microenvironment." (PMID 36601581, 2022). "The results of the present study will contribute to a more comprehensive understanding of potential HMGB1-related molecular mechanisms underlying the clinical prognosis and possible pathogenesis of different cancer types." (PMID 36230798, 2022). "Highly expressed HMGB1 was significantly associated with Overall Survival (OS) for cancers of ACC (p = 0.004), ESCA (p = 0.028), KICH (p = 0.037), KIRC (p = 0.045), LUAD (p = 0.009), PAAD (p = 0.026) and THYM (p = 0.035)." (PMID 35765707, 2022). "HMGB1, a member of the high mobility group box subfamily, has been demonstrated to be associated with various cancer." (PMID 36685879, 2022). "Elevated histone density is associated with global histone acetylation, histone deacetylase inhibitor sensitivity and altered mitochondrial proteome composition, with histone regulator HMGB1 linked to histone density aberrations in many cancer cell lines." (PMID 36030322, 2022). "HN-PIT causes necrosis of cancer cells, which release damage-associated molecular patterns (DAMPs) such as ATP, calreticulin, and high mobility group box 1 (HMGB1)." (PMID 36139573, 2022). "While in certain types of cancer, high levels of circulating HMGB1 have been associated with a poorer prognosis, the elevation of HMGB1 following treatment was previously demonstrated to correlate with improved treatment outcomes." (PMID 36430552, 2022). "OxPt/SN38 causes CRT exposure onthe cancer cell surface and releaseof HMGB-1 and other DAMPs to recruit antigen-presenting cells (APCs)into the tumors." (PMID 36382721, 2022). "The pan‐cancer analysis of HMGB1 in different malignancies demonstrates that the most frequent DNA alterations are amplification, mutations and deep deletions in the TCGA pan‐cancer panel." (PMID 35765707, 2022). "In summary, histone density associates with specific proteome signatures across cancer cell lines, and is linked to the expression of chromatin components, mitochondrial proteins, and known histone regulators (HMGB1, CTSL)." (PMID 36030322, 2022). "Among these peptides, Nal-P-113 demonstrated the best anticancer activity and caused cancer cells to release potent danger-associated molecular patterns (DAMPs), such as reactive oxygen species (ROS), cytochrome c, ATP, and high-mobility group box 1 (HMGB1)." (PMID 35625834, 2022). "NET formation in the hypoxic TME is caused by chemokines and high mobility group box 1 (HMGB1) levels, which have been found to be high in conditioned medium prepared with hypoxic cancer cells." (PMID 36059520, 2022).
cancer (continued). "For example, the expression level of HMGB1 in THYM is statistically positively correlated with the infiltration level of cancer‐associated fibroblasts (cor = −0.413, p = 4.55e‐06) based on the TIDE algorithm." (PMID 35765707, 2022). "Increased HMGB1 expressions are associated with each of the hallmarks of cancer including sustained angiogenesis, evading apoptosis, self-sufficiency in growth signals, insensitivity to inhibitors of growth, inflammation, tissue invasion, and metastasis." (PMID 35610613, 2022). "Dying cancer cells can secrete damage-associated molecular patterns (DAMPs), mainly including high mobility group box 1 (HMGB1), calreticulin (CRT), adenosine triphosphate (ATP) and Type I interferon (Type I IFN)." (PMID 36619616, 2022). "For instance, HMGB1 is associated with infectious and aseptic inflammatory disease states, and cancer." (PMID 36052059, 2022). "Radiation-induced cancer cell damage/death leads to release of damage-associated molecular patterns (DAMPs), including ATP, high mobility group box 1 (HMGB1), calreticulin and heat shock protein." (PMID 34439387, 2021). "Overexpression of HMGB1 is associated with the hallmarks of cancer, which included an unlimited replicative potential, angiogenesis, evasion of apoptosis, insensitivity to inhibitors of growth, inflammation, tissue invasion, and metastasis." (PMID 34778055, 2021). "HMGB1, a damage-associated molecular pattern, has been shown to participate in the growth and progression of cancer." (PMID 34758877, 2021). "In total, of 3,918 cases and 5,296 controls were included in this study to reveal the correlation between HMGB1 rs1045411 polymorphism and cancer risk." (PMID 33628090, 2021). "Until now, many case-control studies have been carried out to explore the relevance of the HMGB1 polymorphism rs1045411 to cancer." (PMID 33628090, 2021). "High-mobility group box 1 protein (HMGB1), which functions as a DNA chaperone and a prototypical damage-associated molecular pattern, plays a paradoxical role in cancer." (PMID 34257571, 2021). "HMGB1 is a recently identified protein associated with cancer growth and metastasis, and represents a new therapeutic target for the treatment of cancer." (PMID 33807620, 2021). "As a damage-associated molecular pattern (DAMP) molecule, HMGB1 was stated that its expression was upregulated in various kinds of cancers." (PMID 34933679, 2021). "We investigated the significance of CML modification in high mobility group box protein-1 (HMGB1), a cytokine that is significantly associated with cancer progression." (PMID 34068442, 2021). "The high-mobility group box protein 1 (HMGB1) rs1045411 polymorphism has been demonstrated to be associated with cancer risk in some studies." (PMID 33628090, 2021). "Further investigations are warranted to elucidate the associations between cancer-derived HMGB1 with its magnitude and influence on lung damage, and the development of postoperative AE-ILD." (PMID 33980944, 2021). "In spite of the considerable efforts to explore the possible relationship between the HMGB1 rs1045411 polymorphism and cancer risk, some limitations of the current meta-analysis should be noted." (PMID 33628090, 2021). "And our results reveal a positive relationship between HMGB1 rs1045411 polymorphism and cancer risk." (PMID 33628090, 2021). "HMGB1 has been previously linked to the induction of autophagy and thought to be a potential for exploiting HMGB1-induced autophagy in cancer therapy." (PMID 33726796, 2021). "Upregulation of MMPs with HMGB1 has been associated with cancer cell proliferation of colon through the RAGE/Snail/NF-κB signalling pathways accompanied by the activation of MMP-7." (PMID 34194625, 2021). "A meta-analysis was applied to elucidate the association between the HMGB1 rs1045411 polymorphism and cancer risk." (PMID 33628090, 2021).
cancer (continued). "CML-HMGB1 activated cancer-associated signals, such as RAGE, AKT, and NF-κB, exceeding the effect of oxidized HMGB1, and promoted proliferation, invasion, survival, stemness, and drug resistance development." (PMID 34068442, 2021). "Chromosomal instability is considered important in the pathogenesis of cancer, and the HMGB1 loss can reduce telomerase activity, decrease telomere length, and increase chromosomal instability 16-19." (PMID 33628090, 2021). "Given the double functions of HMGB1 in modulating inflammation and cancer, we are still uncertain about the underlying relationships between dysregulation of HMGB1 with ESCC." (PMID 34820329, 2021). "When cancer cells die, they release a protein called high mobility group box-1 (HMGB-1) that causes dendritic cells to become activated." (PMID 34683171, 2021). "One of the molecular mechanisms underlying the essential role of NAC1 in cancer cell survival are recently reported to involve in autophagic response mediated by high-mobility group protein B1 (HMGB-1)." (PMID 34416910, 2021). "Human HMGB1 binds DNA without sequence specific recognition and the gene encoding it, HMGB1, is overexpressed in many types of cancer, including those of prostate and ovary." (PMID 34572914, 2021). "HMGB1 overexpression is a hallmark of sepsis, arthritis, neurodegeneration, aging, angiogenesis, and cancer development and metastasis." (PMID 34199060, 2021). "Since HMGB1 overexpression has been associated to cancer in different cell types we looked for evidence of overexpression of the NuRD complex in cancerous cells." (PMID 34572914, 2021). "HMGB1 has been implicated in tumorigenesis, progression, metastasis and chemotherapy resistance of various cancers." (PMID 33925132, 2021). "In a systematic literature review of 18 studies involving 11 cancers, high expression of HMGB1 was associated with poor prognosis." (PMID 34867338, 2021). "The high-mobility group box-1 (HMGB1) protein is implicated in the development of various cancers and their proliferation." (PMID 33122771, 2020). "HMGB1 is a ubiquitous, multifaceted molecule that is increasingly implicated in the pathogenesis of many types of human cancer, driving all of the stages of tumorigenesis." (PMID 32664328, 2020). "HMGB1 is also associated with cancer progression and immune escape, which is able to induce angiogenesis, metastasis." (PMID 33473353, 2020). "High-mobility group protein B1 (HMGB1) is an intracellular protein, which has closely association with cell survival, proliferation and metastasis in various cancers." (PMID 32536835, 2020). "For example, HMGB1 associates with the receptor of advanced glycation end products (RAGE) in cancer." (PMID 32647502, 2020). "In murine cancer models, HMGB1 and S100B induce muscle wasting and this is associated with elaboration of IL-1β and IL-6." (PMID 33291708, 2020). "Some studies have associated HMGB1 SNPs with increased cancer risk, disease susceptibility, severity, and progression, or poorer response to treatment." (PMID 33023053, 2020). "In this study, three antigenic synthetic peptides, which are overexpressed in several cancer types, were covalently linked with HMGB1-derived peptide (HB100-108) as immunoadjuvant via double R linker and loaded into immature DCs." (PMID 32322595, 2020). "Outside the cell, HMGB1 functions as a prototypic damage-associated molecular pattern (DAMP) molecule with established roles in pathobiology such as cancer initiation and progression, toxic shock, and trauma." (PMID 33013860, 2020). "Cancer associated fibroblasts (CAFs) have been shown to secrete HMGB1 via autophagy, which activates TLR-4 receptors expressed by cancer cells to increase the stem cell phenotype and tumor growth." (PMID 32532126, 2020). "Herewe reported that CGA binds with the active site of HMGB1 asproved by molecular docking experiment, thus mitigating itsactivity and ability to cause cancer." (PMID 31485132, 2019).